SIRT1 (sirtuin 1)
Diseases named in the same sentence as SIRT1 in open-access papers (continued):
Sharing a sentence is not in itself a finding about the gene and the disease.
Cognitive impairment (continued). "Conversely, strategies that promote SIRT1 expression have been demonstrated to relieve hippocampal neuron damage and cognitive impairment following CCH." (PMID 40290868, 2025). "Citicoline was also demonstrated to increase the levels of sirtuin 1 (SIRT1), thus reducing inflammation—leading to improved cognitive status and a better quality of life in cognitive impairment." (PMID 41446880, 2025). "Future research should prioritize investigating the functional interplay between SIRT1 and transcriptional regulators (e.g., NF-κB, CREB) in modulating gene expression networks underlying cognitive deficits." (PMID 40621197, 2025). "The findings indicated that baicalein mitigated cognitive impairment, promoted angiogenesis and suppressed neuroinflammation and apoptosis by regulating the SIRT1-mediated Notch1 pathway." (PMID 40290868, 2025). "AAV-mediated Sirt1 overexpression in the hippocampus or systemic administration of the Sirt1 activator resveratrol prevented cognitive impairment and tau hyperphosphorylation via enhancing Sirt1 activity in GBP-treated mice." (PMID 40969938, 2025). "In contrast, Sirt1 activation prevents microglia‐mediated synaptic phagocytosis after anaesthesia and surgery and reverses cognitive deficits." (PMID 40008520, 2025). "Our study found increased tau phosphorylation via Sirt1-CaMKIIα signaling pathway in the hippocampus in aged mice with GBP-induced cognitive impairment." (PMID 40969938, 2025). "Overexpressing Sirt1 protein or enhancing Sirt1 activity with resveratrol ameliorated cognitive impairment and suppressed tau hyperphosphorylation in GBP-treated aged mice." (PMID 40969938, 2025). "The results of our study showed that there was a significant correlation between SIRT1 and PD with cognitive impairment, and further analysis showed that the level of SIRT1 was related to visuospatial/executive function, memory, and language." (PMID 37718350, 2024). "In summary, SYR attenuated cognitive deficits, glial activation, and apoptotic signaling induced by Sev, and these effects were mediated by the SIRT1 pathway, as the inhibition of SIRT1 by EX527 abrogated the protective effects of SYR." (PMID 38622895, 2024). "Taken together, our study found that Res and VitD3 improved locomotor and cognitive deficits, modulated Sirt1 and Lingo-1." (PMID 38684734, 2024). "Previous studies have shown that serum SIRT1 is significantly decreased in patients with cognitive impairment and dementia." (PMID 37718350, 2024). "Neuroinflammation and decreased antioxidant and SIRT-1 signaling contributed to cognitive deficits in aged SAMP8 mice, which are potential therapeutic targets of formononetin in combination with other therapies." (PMID 39234102, 2024). "Relative to chronic stress-induced cognitive impairment, resveratrol led to an overall cognitive enhancement in this context through its action on SIRT1 and the BDNF/CREB pathway." (PMID 39458427, 2024). "The intervention with EX527, a SIRT1 inhibitor, further confirms the pivotal role of SIRT1 in mediating SYR’s protective actions against Sev-induced cognitive deficits, glial activation, and apoptotic signaling." (PMID 38622895, 2024). "Increased miR-34a expression is associated with cognitive impairment and AD-like pathology by targeting alpha secretase (ADAM10), NMDAR2B and SIRT1 RNAs, whose levels are significantly reduced by miR-34a overexpression." (PMID 38612989, 2024). "Triptolide activated the SIRT1/PGC‐1α signaling pathway to improve cognitive impairment in rats with vascular dementia." (PMID 38688894, 2024). "This suggests that the Sirt1/PGC-1α pathway has potential as a therapeutic target for improving cognitive impairment induced by SD in late pregnancy." (PMID 38231482, 2024). "The activated Sirt1/PGC-1α pathway can improve cognitive deficits induced by chronic cerebral hypoperfusion, scopolamine, or a high-fat diet by modulating oxidative stress and neuroinflammation." (PMID 38231482, 2024).
Cognitive impairment (continued). "Studies suggest that activation of SIRT1 inhibits acetylation and phosphorylation of Tau in aged rats, thereby reducing neurodegeneration and cognitive impairments induced by sevoflurane." (PMID 38622895, 2024). "Correspondingly, Nicotinamide, a Sirt1 inhibitor, attenuated cognitive deficits in mice by promoting neuronal survival via the IGF-1pathway81, and through phosphorylation of tau82." (PMID 37898621, 2023). "Sesamol, a nutritional component of sesame, ameliorated neuron damage and cognitive deficits in mice fed a high-fat and high-fructose diet, partly by enhancing the mRNA levels of SIRT1 and PGC-1α." (PMID 37191431, 2023). "According to previous research, SIRT1 is substantially downregulated in the hippocampal neurons of mice with cognitive impairment." (PMID 38027119, 2023). "Here, we evaluate the effects of diet control and swimming or both on the prevention of cognitive impairment by enhancing SIRT1 activity." (PMID 36999158, 2023). "On average, both male and female participants are categorized as having mild cognitive impairment with a homogeneity between the two groups, however, there is a significant difference in the SIRT1 levels (p < 0.05)." (PMID 38132490, 2023). "The results showed that administration of Nano-PSO, which is comprised of fatty acids, led to a recuperation of lost SIRT1 and mitigated the cognitive impairments induced by TBI." (PMID 35566074, 2022). "In our study, we identified exosomes derived from MSCs and demonstrated that MSCs-Exo can ameliorate cognitive impairment by inhibiting hippocampus ferroptosis via activating SIRT1/Nrf2/HO-1 pathway in dNCR aged mice." (PMID 36238648, 2022). "RSV ameliorates sevoflurane-induced cognitive impairment by activating the SIRT1/NF-κBp65 pathway in neonatal mice." (PMID 35386302, 2022). "SIRT1 plays an important role in neurodegenerative diseases and cognitive deficits via regulating the levels of Nrf2 and HO-1." (PMID 36238648, 2022). "Resveratrol ameliorates sevoflurane-induced cognitive impairment by activating the SIRT1/NF-κB pathway in neonatal mice." (PMID 35386302, 2022). "The activation of SIRT1 targeting Nrf2/HO-1 pathway activation can alleviate central nervous system inflammation-induced cognitive deficits." (PMID 36238648, 2022). "Administration of SIRT1 agonist SRT1720 also partially reversed cognitive deficits in mice after anesthesia and surgery." (PMID 36437988, 2022). "Combined with OFT, MWM test and western blotting, we found that Sirt1 knockdown induced hippocampal atrophy was also accompanied by cognitive impairment, activation of hippocampal tau hyperphosphorylation and synaptic damage." (PMID 35668361, 2022). "This work revealed that Sirt1 is an important protective gene against hippocampal atrophy and its induced cognitive impairment during aging, providing potential therapeutic targets for the prevention and intervention of aging-related neuropsychic diseases." (PMID 35668361, 2022). "Collectively, it can be deduced that exogenous H2S mitigates SD-induced cognitive impairment by inhibiting autophagy via hippocampal Sirt-1 of rats." (PMID 36144282, 2022). "In our model, injured mice demonstrated a significant impairment in visual and spatial memory, which suggests SIRT1 involvement in the mechanism contributing to cognitive impairment." (PMID 35566074, 2022). "This research was planned to investigate the potential neuroprotective effect of nanoceria on DOX-induced cognitive impairment and its role in the regulation of the SIRT-1 pathway." (PMID 35893742, 2022). "And pretreatment specific SIRT1 inhibitor EX-527 abolished improving effects of MSCs-Exo in cognitive impairment and ferroptosis of aged mice after surgery." (PMID 36238648, 2022).
Cognitive impairment (continued). "In this study, cognitive function was significantly impaired in the T2DM mice; aerobic exercise improved cognitive impairment through activating the AMPK/SIRT1 signalling pathway and inhibiting the JAK2/STAT3 signalling pathway in T2DM mice." (PMID 35578689, 2022). "The protective effects of MSCs-Exo on cognitive impairment in aged mice were related to its inhibited hippocampus ferroptosis by modulating the activity of SIRT1/Nrf2/HO-1 signaling pathway." (PMID 36238648, 2022). "In conclusion, these findings indicated that MSCs-Exo can ameliorate cognitive impairment by inhibiting hippocampus ferroptosis in dNCR aged mice via activating SIRT1/Nrf2/HO-1 signaling pathway, providing a potential avenue for the treatment of dNCR." (PMID 36238648, 2022). "Changes in Sirt1 expression have been proved to be closely related to the progression of cognitive impairment and AD pathology." (PMID 35668361, 2022). "This work revealed the key role of Sirt1 in maintaining hippocampal volume to prevent cognitive impairment during aging, and provides important targets for the prevention and therapy of AD." (PMID 35668361, 2022). "Taken together, our results suggested that MSCs-Exo effectively ameliorated the cognitive impairment and inhibited hippocampus ferroptosis in dNCR aged mice through a SIRT1-dependent mechanism." (PMID 36238648, 2022). "TBI reduced the levels of SIRT1 in cortex and in the hippocampus 30 days post-injury which was ameliorated by KD, suggesting a potential mechanism contributing to cognitive impairment and improvement in cognitive symptoms when given KD42." (PMID 34876621, 2021). "AT reduced the cognitive impairment induced by a high-fat diet and neurotoxicity induced by amyloid β peptide via Sirt1 activation." (PMID 35096297, 2021). "For example, Resveratrol ameliorated mitochondrial dysfunction and cognitive impairment of AD model mice by activating Sirt1." (PMID 33369003, 2021). "A study demonstrated that Resveratrol increases the SIRT1 expression in the cortex and hippocampus reducing the cognitive impairment." (PMID 34945679, 2021). "As natural selective modulators of SIRT1 signalling through the ERs, dSTACs therefore have the potential to provide all the benefits of oestradiol such as protection from cognitive impairment and metabolic diseases." (PMID 32210296, 2020). "The hyperacetylated tau, at least partially mediated by SIRT1 inhibition, increased tau phosphorylation and contributed to cognitive impairment in the present experimental model." (PMID 33381265, 2020). "Collectively, these results demonstrate that RSV activates SIRT1-dependent mitochondrial biogenesis process and promotes subsequent neuronal restoration, thus protecting offspring rats from NaF-induced cognitive impairments." (PMID 32308752, 2020). "Shen J., Li Y., Qu C., Xu L., Sun H., Zhang J. The enriched environment ameliorates chronic unpredictable mild stress-induceddepressive-like behaviors and cognitive impairment by activatingthe SIRT1/miR-134 signaling pathway in hippocampus." (PMID 35088002, 2020). "In summary, our finding suggested that SIRT1 reduction contributed to tau acetylation and cognitive impairment in aged rats following surgery and anesthesia." (PMID 33381265, 2020). "Taken together, our findings provided the initial evidence that tau acetylation was associated with cognitive impairment in the aged POCD model and paved a promising avenue to prevent POCD by inhibiting tau acetylation in a SIRT1-dependent manner." (PMID 33381265, 2020). "Our previous study found that microglial-derived SIRT1 reduction contributed to neuroinflammation and cognitive impairment in the aged POCD model." (PMID 33381265, 2020). "Supportively, our in vivo study further validated that RSV administration activated SIRT1 expression to improve mitochondrial biogenesis and morphology, thus retarding NaF-induced cognitive defects of offspring rats." (PMID 32308752, 2020).
Cognitive impairment (continued). "In the present study, our findings showed that tau acetylation mediated by SIRT1 deficiency resulted in tau hyperphosphorylation in the hippocampus of the aged POCD model and consequently contributed to cognitive impairment." (PMID 33381265, 2020). "The protective effects of BAI on cognitive impairment in mice appeared to be related to its anti-inflammatory activity in microglial cells, modulating the activity of SIRT1, as well as downregulating the HMGB1 signaling pathway." (PMID 33029280, 2020). "Remarkably, pretreating the model with resveratrol nearly restored the hippocampal expression of SIRT1, suppressed the levels of tau acetylation and phosphorylation, and finally mitigated the cognitive impairment." (PMID 33381265, 2020). "Another study has shown that resveratrol ameliorated the Aβ-induced cognitive deficits in AD mice by upregulation of SIRT1 and downregulation of NF-κB/IL-1β/NLRP3." (PMID 33014276, 2020). "ADAM10 activation by SIRT1 in a mouse model of AD significantly attenuated Aβ deposition and cognitive deficits." (PMID 30249814, 2019). "It has been documented that SIRT1 mediates the roles of H2S in attenuating chronic restraint stress-induced cognitive impairment and inhibiting homocysteine-induced endoplasmic reticulum stress in PC12 cells." (PMID 31481873, 2019). "A clear decline in SIRT1 levels is observed in patients with AD and mild cognitive impairment (MCI) as compared to healthy subjects." (PMID 30871086, 2019). "Taken together, we identified a critical role of H2S in the protection against CRS-induced hippocampal damage and cognitive impairment, as a result of upregulation of hippocampal Sirt1." (PMID 29245987, 2017). "Nicotinamide, an inhibitor of SIRT1, has been shown to attenuate cognitive deficits of 3xTg-AD mice via inhibition of SIRT1 and phosphorylation of tau." (PMID 29164153, 2017). "Together, these results suggest that H2S meliorates CRS-induced hippocampal damage and cognitive impairment by upregulation of hippocampal Sirt1." (PMID 29245987, 2017). "These discoveries together suggested that H2S attenuates CRS-induced hippocampal damage and cognitive impairment by upreglulation of hippocampal Sirt1." (PMID 29245987, 2017). "We found that H2S attenuated hippocampal damage and cognitive impairment, coupled with increasing the expression of Sirt1 in the hippocampus of CRS-exposed rats." (PMID 29245987, 2017). "In conclusion, our results revealed that H2S suppressed CRS-evoked hippocampal damage and cognitive impairment, which is mediated by the upreglulation of hippocampal Sirt1 in CRS-exposed rats." (PMID 29245987, 2017). "In conclusion, supplementation of testosterone prevented cognitive impairment of SAMP8, in which testosterone secretion was decreased in association with the senescence of testis Leydig cells, through an eNOS/SIRT1-dependent mechanism." (PMID 22238626, 2012). "Our study suggests that EA may improve cognitive impairment in aged mice with PND by inhibiting ferroptosis in hippocampal neurons through the SIRT1/NRF2/GPX4 pathway." (PMID 41527519, 2026). "Notably, SIRT1 overexpression in saline mice recapitulated morphine-induced cognitive impairments, indicating that SIRT1 elevation alone is sufficient to drive maladaptive plasticity." (PMID 40621197, 2025). "Hippocampal overexpression of Sirt1 or systemic administration of resveratrol boosted Sirt1 activity, inhibited CaMKIIα protein expression and tau phosphorylation, and thereby prevented cognitive impairment in GBP-treated aged mice." (PMID 40969938, 2025). "A reduction in Sirt1 during the aging process is known to contribute to cognitive impairment." (PMID 41154548, 2025). "However, NMN supplementation notably improved neurological function and mitigated cognitive deficits induced by D-gal, with Sirt1-mediated pathways playing a pivotal role in the neuroprotective effects of NMN." (PMID 40276601, 2025).
Cognitive impairment (continued). "Prenatal intermittent hypoxia (PIH) exposure could provoke inflammation and synaptic dysfunction leading to cognitive impairment, resveratrol potentially reversing cognitive deficits by influencing the SIRT1/HIF‐1α pathway." (PMID 40084394, 2025). "Adeno-associated virus (AAV) vector mediated overexpression of Sirt1 in the hippocampus or systemic administration of Sirt1 activator resveratrol curbed GBP-induced cognitive impairments and suppressed tau phosphorylation." (PMID 40969938, 2025). "Indeed, other studies previously reported on neuroprotective effects of SIRT1 and overexpression of miR-34a-5p in cognitive impairment and AD-like pathology." (PMID 41277875, 2025). "Collectively, our outcomes propose that RES may counteract cognitive impairments in rats resulting from maternal hypoxia during pregnancy by modulating the hippocampal SIRT1/HIF‐1α pathway." (PMID 40084394, 2025). "We hypothesized that niacin supplementation may alleviate WBI-induced behavioral and cognitive impairments by reducing oxidative stress and inflammation through modulation of the SIRT1/CREB/BDNF and SIRT1/SIRT6 signaling pathways." (PMID 40508105, 2025). "Therefore, enhancing Sirt1 levels can be significant in preventing or treating cognitive impairment due to aging." (PMID 41154548, 2025). "Additionally, SIRT1-mediated ferroptosis is significant in neurodegenerative diseases and cognitive disorders, with activation of the SIRT1/Nrf2 pathway shown to inhibit oxidative stress and ferroptosis, improving cognitive function." (PMID 40109363, 2025). "Our research indicates that PIH exposure could provoke inflammation and synaptic dysfunction, with RES potentially reversing cognitive deficits by influencing the SIRT1/HIF‐1α pathway." (PMID 40084394, 2025). "For instance, studies have shown that higher circulating TMAO levels can aggravate cognitive impairment by downregulating hippocampal SIRT1 expression in models of vascular dementia, and that TMAO promotes inflammatory responses through signaling pathways involving SIRT1 suppression." (PMID 41249794, 2025). "This decrease implies that synaptic plasticity disruptions could be the root of cognitive impairments linked to PIH, possibly because of the disruption of the SIRT1/HIF‐1α signaling pathway." (PMID 40084394, 2025). "Patients with AD and mild cognitive impairment have been found to exhibit lower levels of SIRT1 compared to healthy individuals, indicating that measuring serum SIRT1 levels could potentially serve as an early biomarker for AD diagnosis." (PMID 38504306, 2024). "Several molecular events such as neuroinflammation and decreased antioxidant and SIRT-1 signaling could contribute to cognitive deficits in aged SAMP8 mice and are potential targets of therapeutics like FMN." (PMID 39234102, 2024). "The role of nicotinamide in autophagy and SIRT1 may vary depending on certain conditions and may promote cell survival by inducing SIRT1-dependent autophagy and improving cognitive impairment." (PMID 38673986, 2024). "Pretreatment with melatonin could prevent cognitive defects and neuronal disturbances by strengthening the deacetylation of SIRT1 substrates." (PMID 39056330, 2024). "According to the ROC curve analysis, the AUC values of PD with cognitive impairment based on plasma SIRT1 levels and whole-brain GM volume, respectively, were 0.812 and 0.812; the sensitivity values were 78.3% and 78.3%, and the specificity values were 83.3% and 75%." (PMID 37718350, 2024). "Taken together, these results suggest that SS‐31 could improve CSD‐induced mitochondrial biogenesis dysfunction, inflammatory response, synaptic dysfunction, and cognitive impairment by increasing SIRT1 expression levels." (PMID 38688894, 2024).